BMP4 (bone morphogenetic protein 4)
Diseases named in the same sentence as BMP4 in open-access papers (continued):
Sharing a sentence is not in itself a finding about the gene and the disease.
Strabismus (1 paper, 2025). A misalignment of the eyes so that the visual axes deviate from bifoveal fixation. "The mechanism by which BMP-4 affects EOM changes is not yet clear, and further research is needed to clarify the specific role of BMP-4 in the pathogenesis of strabismus and its safety and effectiveness for the treatment." (PMID 40696418, 2025). "In addition to the effects of BMP-4 on EOMs, studies in the field of cardiology found that MMPs may affect myocardial contractile force and lead to heart failure, suggesting that MMPs may also affect the contractility of EOMs, and the ECM is disrupted in the strabismus patients." (PMID 40696418, 2025).
T-cell lymphoma (1 paper, 2019). "RQ-PCR analysis of BMP4 in T-cell lymphoma cell lines and normal primary hematopoietic cells confirmed strong overexpression in DERL-2." (PMID 31143370, 2019).
thoracic aortic aneurysm (1 paper, 2024). An aneurysm formed in the wall of the proximal portion of the descending aorta proceeding from the arch of the aorta. "The aim of this study was to investigate for the first time the effects of BMP-4 on the VSMC phenotype and to understand its role in the development of thoracic aortic aneurysms (TAAs)." (PMID 38727271, 2024).
Truncus arteriosus (1 paper, 2019). A single arterial trunk arises from the cardiac mass. "While Bmp7 null mutants do not show defects in heart development, conditional deletion of both Bmp7 and Bmp4 from progenitors of the secondary heart field leads to persistent truncus arteriosus." (PMID 31566563, 2019).
ulcers (1 paper, 2021). "Biopsy ulcers in Vil1-Grem1 animals wererapidly covered by WAE, whereasepithelial Bmp4 expression inVil1-Cre;Rosa26Bmp4 micedelayed coverage by WAE and retarded closure." (PMID 33819486, 2021).
Varicose veins (1 paper, 2021). Enlarged and tortuous veins. "BMP4-pSMAD5 signaling is an important mediator of EndMT in varicose veins." (PMID 34944071, 2021). "BMP4-pSMAD5 could emerge as a target for small molecule therapy in patients with varicose veins." (PMID 34944071, 2021).
vascular dementia (1 paper, 2022). A degenerative vascular disorder affecting the brain. "BMP4 is upregulated in the brains of patients with vascular dementia as well as in the hypoperfused mouse brains undergoing bilateral common carotid artery stenosis." (PMID 35948662, 2022).
venous insufficiency (1 paper, 2021). Impaired venous blood flow or venous return (venous stasis), usually caused by inadequate venous valves. "In vitro flow-based assays using human vein, endothelial cells cultured in microfluidic chambers show that even minimal disturbances in shear stress as may occur in early stages of venous insufficiency induce BMP4-pSMAD5-based phenotype switching." (PMID 34944071, 2021).
yolk sac tumours (1 paper, 2023). "Intriguingly, SOX17 and BAMBI, implicated in yolk sac tumours, were increased in TCam-2 cells by both activin A and BMP4 exposure at 48 h." (PMID 37048077, 2023).
Zinc deficiency (1 paper, 2025). A deficiency of the essential metal Zinc; an essential cofactor for many enzymes. "Zinc deficiency increases expression of bone morphogenetic proteins (BMP2, BMP4)." (PMID 41517264, 2025).
tumor (264 papers, 2004 to 2026). "All 10 DEGs found in the patients who lived in Sao Paulo city compared to the MRSP were associated with cell proliferation and tumor development (BMP4, CTNNBP1, DISP1, DVL1, ERBB4, PRLR, WNT5b, LEF1, PGR, and PTEN)." (PMID 36768749, 2023). "In a murine model of VEGF-D-driven tumour metastasis, reduced expression of bone morphogenetic protein-4 (BMP-4) in HEVs was associated with a remodelling of HEVs towards a flat, thin-walled phenotype." (PMID 33132107, 2021). "The tumor sphere formation assay results revealed that silencing BMP4 in BIRC3 knockout U251 cells significantly induced tumor sphere formation and rescued the loss of stemness which was previously induced by BIRC3 knockout (p < 0.05)." (PMID 35008722, 2021). "THBS1 underlies the inhibitory role of BMP4 in tumor angiogenesis, which is mainly achieved by a network that VEGF expression is reduced by BMP4 in a THBS1-dependent manner in the tumor microenvironment." (PMID 31847842, 2019). "Immunohistochemistry studies associated BMP-4 expression with low proliferation tumours, but also increased recurrence." (PMID 28733469, 2017). "Double staining for F4/80 and BMP4 showed that the majority of spleen macrophages expressing F4/80 were associated with BMP4 expression in tumor-bearing mice." (PMID 25822717, 2015). "rs4444235 has been recently reported to be a cis-acting regulator of BMP4 gene; in this study, the C allele was preferentially retained in tumor tissues (p = 0.0023)." (PMID 24968322, 2014). "Given that subtle changes in distant regulatory elements result in low-penetrance of cancer susceptibility and play a role in tumor cell development, alterations in several loci of BMP4 at 14q22 and GREM1 at 15q13 affect TGFβ signaling." (PMID 24968322, 2014). "The expression of BMP-4 in HCC was associated with number of tumor nodules, Edmondson grade, TNM stage, and vascular invasion." (PMID 24779016, 2014). "Under a low tumor burden setting, the BMP-4 virus caused tumor regression and kept the tumor in check to below the signal when the tumor was first infected up to 51 dpi." (PMID 23800258, 2013). "Using these we examined tumors for loss of heterozygosity indicative of BMP4 having a tumor suppressor role." (PMID 20949628, 2011). "Although we were unable to demonstrate differential methylation of the putative promoter region of BMP4 we cannot fully exclude the possibility of inactivation of the wild-type allele through hypermethylation as a basis of tumor development." (PMID 20949628, 2011). "Moreover, several FAM20C substrates such as insulin-like growth factor-binding proteins (IGFBPs), osteopontin (OPN), bone morphogenetic protein 4, fibronectin 1, and fetuin-A (Fet A) are associated with the apoptosis, invasion, and metastasis of tumor cells." (PMID 39790934, 2025). "However, consistent with results from the other two models, the anti-metastatic effect of BMP4 was retained in 4T1.2 tumor-bearing mice despite total loss of SMAD4." (PMID 38689334, 2024). "Furthermore, BMP4 activates cancer-associated fibroblasts, which inactivate NK cells and allow tumor cells to evade the immune system." (PMID 35845139, 2022). "Identification of distinct mechanisms underlying the context-specific BMP4 interactions within the tumor microenvironment could provide therapeutic targeting of the BMP4 pathway according to specific tumor phenotypes." (PMID 35694408, 2022). "In addition, tumor-derived BMP4 was shown to induce M2 macrophage polarization associated with tumor progression." (PMID 36532749, 2022). "Furthermore, activated cancer-associated fibroblasts by BMP4 switch NK cells to an inactive phenotype to facilitate the immune escape of tumor cells." (PMID 35173763, 2021). "Moreover, transcript levels of genes associated with CRC susceptibility loci (e.g., Grem1 and Bmp4) and tumor development and invasion (e.g., Wnt5a, Ereg, Mmp3, Mmp13, Timp1, Saa3, Ptgs2, and Acsl4) were elevated in IL-11+ fibroblasts." (PMID 33863879, 2021).
tumor (continued). "BMP4‐treatment also prevented bone loss in the scaffolds, most likely due to reduced tumor load." (PMID 31956851, 2020). "Interestingly, the tumor-promoting effects shown for BMP4 stemmed from mutations in BMP4 or Smads while the tumor-promoting effects of BMP7 did not depended on Smad4." (PMID 28009989, 2017). "In addition, in recent years the contribution of BMP4 to cancer pathogenesis has been emphasized reporting both protumoral and antitumoral effects of this morphogen, depending on the kind and level of risk of tumor." (PMID 24400095, 2014). "As a member of the transforming growth factor β family, bone morphogenetic protein 4 can affect cell proliferation and differentiation of multiple organs, and tumor development." (PMID 39790934, 2025). "However, groups 1 and 3 both contain a number of virtual patients with tumor characteristics that are associated with poor response to BMP4, therefore diluting the overall observed benefit of BMP4, resulting in many fewer trials identifying BMP4 as a potential treatment." (PMID 41279885, 2025). "In the corticotroph tumor cell line AtT20, changes in methylation and histone modifications account for decreased expression of BMP4." (PMID 40257628, 2025). "Huang etal.‘s research in cervical carcinogenesis proved that FTO accelerates tumor progression by eliminating m6A methylation from Bone Morphogenetic Protein 4 (BMP4) mRNA." (PMID 39904996, 2025). "The expression of BMP4 is often diminished in poorly differentiated and aggressive NB cases, suggesting its potential role as a tumor suppressor." (PMID 40429864, 2025). "Single-cell RNA-seq showed BMP4 enrichment in cancer cells and cancer stem cells, supporting its role in tumor metabolism." (PMID 41169612, 2025). "Retinoic acid induces BMP4 expression, while somatostatin analogs enhance BMP4 signaling in corticotroph tumor cells." (PMID 40257628, 2025). "We examine the differential responses of PN- and MES-like cells from the same tumor to BMP4, with a focus on the role of the cyclin-dependent kinase (CDK) inhibitor p21Waf1/Cip1 (p21) in this process." (PMID 40362216, 2025). "Given the tumor-promoting effects of senescent cells, their potential induction by BMP4 should be carefully considered when evaluating BMP4 as a differentiation therapy in a clinical setting." (PMID 40362216, 2025). "Mechanistically, CHRDL1 exerts its tumor-suppressive effects by antagonizing the BMP4/SMAD signaling pathway." (PMID 40837015, 2025). "When presented on gPA, BMP-4 directed pGBM cells to become less stem cell-like which slowed tumor growth in a mouse model." (PMID 41624070, 2025). "BMPs promote malignant phenotypes in several tumor types, and the expression of BMP4 and BMP9 is induced in HCC." (PMID 39457709, 2024). "As expected, enforced expression of BMP4 in 231-HM primary tumours led to a reduction in the levels of total and free cholesterol." (PMID 39273106, 2024). "To optimize a future clinical trial, we wanted to assess the effectivity of combination therapy with TMZ + BMP4 in cultured tumor cells of a group of GBM patients." (PMID 39337661, 2024). "Consistent with earlier studies, we found that a commonly used statin, lovastatin, suppressed spontaneous metastasis to the lungs in the triple-negative MDA-MB-231HM tumours that had negligible BMP4 expression." (PMID 39273106, 2024). "The levels of ALDH1A1 and BMP4 were also high in the METABRIC miR-18a/low tumours on analysis of the DEGs (p < 0.05)." (PMID 38786043, 2024). "We confirmed the observed transcriptional upregulation of ITGB4 and the downregulation of ENPP1 and HMGCS1 in BMP4-expressing primary tumours at the protein level." (PMID 39273106, 2024). "RNA sequencing revealed genes whose expression was altered by the presence of BMP4 in the tumour cells." (PMID 39273106, 2024). "The luciferase signal that is still evident in the mice expressing BMP4 is due to regrowth of the inguinal mammary gland primary tumor after resection." (PMID 38689334, 2024).
tumor (continued). "Later on, it was published that BMP4 impairs the tumor-initiating capacity of GSCs by reducing cell proliferation and increasing the expressions of differentiation markers of astrocytic, neuronal, and oligodendrocyte lineage." (PMID 38256140, 2024). "This reduction was generally the largest after the simultaneous administration of TMZ + BMP4, with the exception of cultured tumor GS502." (PMID 39337661, 2024). "Since BMP4 is a secreted cytokine, this leaves open the possibility that BMP4 acts in a paracrine manner to trigger changes in the tumor microenvironment to suppress metastasis." (PMID 38689334, 2024). "Following the reduction of Nog, Bmp4 expression was reversed in KO tumor epithelial cells in the scRNA-seq data." (PMID 38659853, 2024). "Tumor cell expression of MYO1F was increased to a greater degree by BMP4 in the presence of SMAD4 than in its absence." (PMID 38689334, 2024). "Among the tumor suppressor roles of BMPs, they have been reported to induce cancer stem cell differentiation in colorectal CSCs by BMP4 and in GSCs by BMP4 and BMP7." (PMID 38256140, 2024). "The in vivo xenograft experiments revealed that BMP4 promoted glycogen accumulation and tumor growth, which were effectively diminished by BAY-876." (PMID 37443106, 2023). "The protein levels of BMP4 in tumor tissues (n = 8) from frozen tissue samples were analyzed by western blotting." (PMID 37370018, 2023). "Detailed analysis indicates that BMP4 significantly promoted tumor volume and weight, which was significantly blunted by BAY-876 after 4 weeks." (PMID 37443106, 2023). "And, BMP4 was significantly upregulated in tumor tissues compared with adjacent normal tissues of CRC (P < 0.001)." (PMID 37370018, 2023). "Lastly, the in vivo effect of BMP4-regulated SLC2A1 on HCC tumor growth was assessed in a xenograft model of HCC." (PMID 37443106, 2023). "Contrarily to breast, colorectal and ovarian cancer, high expression of BMP4 in hepatocellular carcinoma promotes tumor progression." (PMID 37529610, 2023). "Accessed 20 Aug 2021), we first demonstrated that the expression of BMP4 was higher in the HCC tissues than that in the adjacent non-tumor tissues." (PMID 37443106, 2023). "The elevated expression of BMP4 in HCC tumor tissues was highly correlated with hepatic glycogen accumulation in clinical samples." (PMID 37443106, 2023). "On the other hand, higher expression of BMP4 was observed in locally advanced Luminal B tumours and elevated GDF15 expression in those T3 and T4 tumours, of both Luminal B and TNBC subtypes, with poor OS." (PMID 37333824, 2023). "Microarray analysis showed that the release of CXCL12, IL-1, IL-6, and bone morphogenetic protein 4 (BMP4) by tumor stroma participates in the recruitment of monocytes and TAMs into OSCC tumors." (PMID 37221555, 2023). "Restored BMP4 expression or therapeutically administered BMP4 protein sensitizes cancer cells to anoikis, reduces the number of circulating tumor cells and the extent of metastasis, thereby resulting in increased survival." (PMID 35846378, 2022). "On the one hand, BMP4 promotes tumor growth by directly stimulating the expression of genes related to tumor cell proliferation and migration." (PMID 35401213, 2022). "Specifically, conditioned media followed by the addition of tumor cell supernatant favors an M2-like polarization of macrophages through BMP4-dependent signaling." (PMID 35053451, 2022). "ASPN binds to BMP-4, inhibiting the differentiation of MSCs into CAFs and leading to the migration of tumour cells and MSCs." (PMID 35869057, 2022). "For instance, in prolactin tumors, BMP4 facilitates the expression of proliferation-related genes such as C-MYC to provoke tumor cell proliferation." (PMID 35401213, 2022). "MSC-derived CAFs can be recruited to the dysplastic stomach in a TGF-β- and SDF-1α-dependent manner and express IL-6, Wnt5α, and BMP4 and have DNA hypomethylation, leading to tumour growth." (PMID 35869057, 2022).
tumor (continued). "BMP4 is another cytokine whose expression is significantly lower in glioma tumor tissue compared to adjacent normal tissue." (PMID 36010607, 2022). "Intraperitoneal treatment with BMP-4 suppressed tumor angiogenesis and reduced tumor formation in xenograft and allograft models of some cancer cells." (PMID 35693928, 2022). "An extensive study using 40 different human GBM-initiating cell cultures demonstrated an extensive diversity in the inhibitory effect of BMP4 on the tumor growth between cell lines." (PMID 36010607, 2022). "The expression levels of BMP4 have been extensively studied in various cancer cell lines and tumor tissues of human and animal origin, by a variety of methods." (PMID 35694408, 2022). "We then analyzed the expression of BMP4 and CD31 in these tumor tissues by immunohistochemistry analysis and found Ibrutinib treatment enhanced BMP4 expression and suppressed CD31 levels." (PMID 36145624, 2022). "BMP4 can act on tumor growth directly or indirectly by interacting with cytokines or affecting downstream gene expression." (PMID 35401213, 2022). "In particular, BMP-4-expressing MSCs efficiently suppressed tumor growth and prolonged the survival of glioma-bearing mice." (PMID 35631698, 2022). "Similar in hGSCs, BMP4 also shown ability to drive astroglia differentiation to inhibit tumor cell proliferation." (PMID 36316503, 2022). "In an in vivo model of prostate cancer, BMP4 favors tumor growth in bone by tumor-induced osteogenesis." (PMID 33921760, 2021). "BMP-4 is involved in inhibition of metalloproteinase-9, which is locally produced by tumor and through the degradation of the extracellular matrix, increased proliferation and invasiveness of tumor." (PMID 34501309, 2021). "To validate BIRC3 modulation of stemness genes in vitro, we further measured relative expression of CD133, ABCG2 and BMP4 using mRNA samples extracted from xenograft tumor tissues." (PMID 35008722, 2021). "Next, we performed tumor sphere assay to determine if BMP4 signaling suppression directly impacted upon GBM cell self-renewal phenotype and neurosphere formation." (PMID 35008722, 2021). "In vitro study showed that BMP-4 suppressed in paracrine mechanism tumor angiogenesis process via the induction of TSP-1." (PMID 34501309, 2021). "Strikingly, the tumor burden was reduced in AAV8‐BMP4 mice compared with the AAV8‐CTRL mice, suggesting that increased circulating BMP4 reduced tumor growth." (PMID 31956851, 2020). "In NMIBC these TAMs are induced and maintained by Bone Morphogenetic Protein 4 (BMP4) secreted by the tumor cells." (PMID 32133299, 2020). "Taken together, these data demonstrated that AAV8‐BMP4 gene therapy lead to the production of high amounts of circulating, biologically active BMP4 that reduced tumor growth." (PMID 31956851, 2020). "In light of the molecular background differences, BMP4 action needs to be interpreted with respect to the distinct features of each tumor group." (PMID 32102285, 2020). "A previous report linked BMP signaling with RUNX3 (a tumor suppressor) in colorectal carcinoma, where the BMP-2 and BMP-4-mediated upregulation of RUNX3 expression inhibited tumor progression." (PMID 32731498, 2020). "It is still unclear how BMP4 affects tumor‐bearing bone and the possibility of combining BMP4 therapy with anti‐resorptive treatment such as denosumab or bisphosphonates should be explored in future studies." (PMID 31956851, 2020). "We show here that BMP4 treatment inhibited tumor growth in vivo, in line with previous studies examining effects of BMP4 on tumor cell survival in vitro." (PMID 31956851, 2020). "Previously, we synthesized a heparin binding domain peptide (HBP) derived from human heparin binding domain of BMP4 and evaluated its biological significance in tumor targeting and anti-angiogenesis." (PMID 32549254, 2020).